AR (androgen receptor)
Diseases named in the same sentence as AR in open-access papers (continued):
Sharing a sentence is not in itself a finding about the gene and the disease.
tumor (continued). "Here, we profiled the expression of AR in various nonmalignant bladder and UCC specimens to correlate AR levels with gender and tumour stage." (PMID 33797847, 2021). "A later study suggested that a selective AR modulator (SARM)/agonist, rather than ENZ, would be capable of inhibiting ER+ BCa tumor growth." (PMID 34137734, 2021). "We identified a Methylation Classifier for Androgen receptor activity (MCA) signature, which separated metastases into two clusters (MCA positive/negative) related to tumor characteristics and patient prognosis." (PMID 34193246, 2021). "Moreover, LMTK2 down-regulation obtained in PCa LNCaP cell line promotes tumour-forming capacity and proliferation, suggesting that the decrease in LMTK2 expression in PCa patients may promote tumour cells’ proliferation by enhancing AR transcriptional activity." (PMID 34064250, 2021). "A subset of UCC tumours, both NMIBC and MIBC, expressed AR mRNA levels above those detected in nonmalignant bladder urothelium specimens." (PMID 33797847, 2021). "In a meta-analysis, AR status in UBC correlated neither with patient gender, nor with tumor size, stage, grade, or progression." (PMID 34768683, 2021). "When AR was negative, TNBC discordance rate between primary, metastatic, and recurrent tumor decreased." (PMID 33915941, 2021). "On the other side, previous publications reported that CD8+ were more frequent in AR+ than AR− tumours, in contrast to our study which showed that neither CD8 nor CD4 were statistically different between AR+ and AR− tumours." (PMID 35047068, 2021). "This will ensure that we pursue therapy, rather than mere drug development, to solve the challenges of tumor heterogeneity, e.g., treating both AR+, PSA-producing, differentiated progeny cells and AR-, non-PSA producing, stem-like progenitor cells." (PMID 34439162, 2021). "qRT-PCR of the lysate of cells captured in the microchannels indicated the presence of cells expressing AR and/or KLK3 but not necessarily that of tumor-derived PCA3 and PSMA genes." (PMID 34771706, 2021). "In multivariate analyses, higher tumor size (p = 0.024), no ACT (p < 0.001), and AR/Cath-D co-expression (p = 0.034) were independent prognostic factors of worse OS." (PMID 32429078, 2020). "Current literature suggests, however, that regardless of tumor type, FOXA1 is an important cofactor for directing the transcriptional activity of AR." (PMID 33062889, 2020). "We determined that C‐26 cells and tumor tissue express the androgen receptor (AR), but did not detect direct effects of DHT treatment on C‐26 cell viability capable of explaining reduced tumor volumes in the DHT monotherapy group." (PMID 31930715, 2020). "This relationship was confirmed in patients’ tissue samples, with a negative correlation between AR and SRF expression in CRPC bone metastases and a positive correlation in androgen-naïve primary tumours." (PMID 33260953, 2020). "AR was expressed in a median of 32.9% of CD163 and/or HLA-DRA and/or CD14 expressing cells in the Tumour area, which was not significantly different from cells in the tumour border or in the distant area (median 34.2% and 35.2%, respectively)." (PMID 32908142, 2020). "Tumour cells harbouring ARVs lack of ligand-binding domain (LBD), enable cells to bypass the need of androgens because AR can become constitutively active." (PMID 32131560, 2020). "The PCSCs isolated from AR-negative DU145 cells show higher expression of CD44, CD24, integrin α2β1, cellular reprogramming factor SOX2, and exhibit tumor-initiating potential and self-renewal ability." (PMID 32754615, 2020). "While tumor cells in PT strongly expressed PSA and AR, those in CDX tumor were negative for both proteins." (PMID 32313004, 2020).
tumor (continued). "Therefore, castration or the standard AR antagonist treatments, such as bicalutamide and enzalutamide, commonly result in the unwanted activation of PI3K/AKT signaling, which may lead to anti-apoptotic activity in PCa cells and thus render tumor cells resistant to the therapies." (PMID 31428587, 2019). "Expression of the AR and CK8 appeared in both E-cadherin positive and negative tumor cells (Fig 6E3 and 6E5)." (PMID 31658259, 2019). "Regarding subtypes, high AR mRNA levels were frequent in HER2-positive (61.3%, 92/150) and luminal tumours (60.0%, 96/160) but almost absent in triple-negative tumours (4.3%, 3/69) (p < 0.0001)." (PMID 31728025, 2019). "Before classification of samples into ER+ BRCA/AR+ PRAD and PRAD tumor and normal breast and prostate samples, a first non-supervised analysis was intended to visualize samples’ grouping in a reduced dimensional space." (PMID 31238876, 2019). "For AR, the increased signal in epithelium is more drastic in the PCa than in the PNT samples, with very weak to negative expression in tumour stroma." (PMID 30254333, 2018). "The significant negative correlation of AR expression with the Karnofsky performance score obtained from the detailed correlation between AR expression and clinical parameters according to the TCGA dataset, may suggest that there is a correlation between AR expression and tumor aggressiveness." (PMID 29731997, 2018). "Notably, under conditions of AR down-regulation, such as those that may occur during aging or inflammation, CARNs that lack tumor suppressors such as PTEN may represent a latent target for subsequent oncogenic events that can confer tumor growth, such as those activating the ERK MAP kinase pathway." (PMID 29334357, 2018). "Another study, using stromal and epithelial cells in AR-knockout TRAMP mice, showed that the lack of expression of this receptor leads to a decrease of tumor size, severity and metastatic invasiveness, and testosterone level reduction." (PMID 28499383, 2017). "Despite being used alongside ectopic hormone replacement, WCE remained effective in attenuating tumor growth and metastasis, suggesting that WCE regulated the AR and downstream activities rather than the physiological levels of androgens." (PMID 29066975, 2017). "We also ascertained that AR mRNA levels are higher in shTRX1 tumors and do not track with PSA levels which, as expected from the tumor volumes, are higher in the shLuc tumors." (PMID 29089489, 2017). "Due to primary tumor unavailability or absence of tumor cells, FISH for AR amplification was feasible in 15/28 (54%) patients, and ERG status by IHC in 19/28 (68%) patients." (PMID 27391263, 2016). "The EPT3-M1 cells which were derived from a metastasis of the orthotopic mouse tumor EPT3-PT1 were analyzed using RNA-seq technology, revealing that neither the AR nor its classical target gene expression were affected by 10 nM R1881 for 48 hours." (PMID 27378372, 2016). "Immunohistochemical evaluation showed that the tumor cells were positive for cytokeratin AE1/AE3, CAM5.2, vimentin, prostate specific acid phosphatase, and androgen receptor and negative for PSA, S-100, CD34, CD68, and smooth muscle actin." (PMID 27843661, 2016). "Such neoplasms seldom occurred in parental TRAMP mice otherwise prone to adenocarcinomas and were characterized for being androgen receptor negative, highly proliferative and endowed with neuroendocrine (NE) features." (PMID 26700622, 2016). "Consistent with p63, p40 and AR-status in human SDCs, these oncogenic KRAS-expressing sarcomatoid tumor cells were negative for the expressions of these markers." (PMID 26289340, 2015). "The fact that AR also showed no prognostic ability after EBRT illustrates the differences in tumour biology between castration resistant and castration sensitive tumours." (PMID 26504789, 2015).
tumor (continued). "LNCaP cells are an androgen-dependent PrC tumor cell line; while PC3 cells are androgen-independent (PC3 cells do not have a functional androgen receptor and cannot produce PSA)." (PMID 24555771, 2014). "The corresponding HPCa101 xenograft tumor derived from pieces implant showed an undifferentiated morphology, was negative for PSA and p63 and weakly positive for AR, and contained CK8+ and CK5+ epithelial cells." (PMID 23451107, 2013). "In contrast to the original tumor tissue, the CD133+ PPT2 cells did not express AR and PSA, which is in line with other reports, and only a small fraction of the PPT2 cells express p63." (PMID 24086245, 2013). "However, multiplex analysis of the cytokine production by the PCa cells after 3 and 5 day of AR activation revealed significant decrease in at least seven major growth and inflammatory factors, suggesting that AR-dependent senescence does not incur SASP and associated tumor-promoting effects." (PMID 22403609, 2012). "Disseminated tumor cells (occult metastases) are detectable by immunohistochemical markers (keratins, PSA, androgen receptor) in lymph nodes qualified as negative (pN0) upon histological examination." (PMID 22229096, 2012). "In addition, we also tested whether let-7c can suppress tumor growth of AR-negative xenografts." (PMID 22479342, 2012). "5-aza-CdR anti-tumor activities were similar in LNCaP and PC3 cells, the latter lacking a functional AR." (PMID 21980513, 2011). "It is also possible that AR-regulated PSA is still responsive to anti-androgens, whereas tumour growth is independent of androgens and is responsive to other signalling pathways such as mTOR." (PMID 20842117, 2010). "Thus, although AR is functional in most recurrent tumors, disrupting AR signaling once the resistant phenotype is established, may not be sufficient to halt the tumor growth." (PMID 17925854, 2007). "Beyond its metabolic role, C/EBPβ may also influence tumor aggressiveness by activating genes involved in mitotic integrity, such as KIFC1, in AR-negative triple-negative breast cancer." (PMID 41596564, 2026). "However, AR expression has also been detected in more aggressive and poorly differentiated tumors, particularly in cases that are estrogen receptor-negative, where ARs may contribute to tumor progression by modulating signaling pathways involved in cell-cycle regulation and survival." (PMID 40286049, 2025). "Tumor cells circumvent the lack of circulating androgens by elevating 5 alpha (α)-reductase, which converts dehydroepiandrosterone and androstenedione to DHT, leading to enhanced AR activation." (PMID 40051495, 2025). "Interestingly, the authors showed that GPX4’s expression was dependent on androgen receptor (AR) signalling, but treating the tumours with AR inhibitors did not prime LAR tumours for ferroptosis." (PMID 40136651, 2025). "However, this study does not involve changes in the Forkhead domain and mainly investigates the impact of basal FOXA1 levels on tumor biology, given that PC-3 and DU145 are AR-negative cell lines." (PMID 41330917, 2025). "In this study, we evaluated the predictor variables of our previous TNBC subtype classification, p16 and AR expression and TIL scores, on whole slides, which are used in pathology laboratories, rather than TMAs to capture the overall tumor biology and to improve subtype classification." (PMID 38760384, 2024). "Recently, it has been established that androgen receptors are present in higher-stage tumors regardless of gender, and the assumption that AR-positive RCC has intratumoral steroidogenesis and that antiandrogen therapy can lead to tumor suppression has been studied." (PMID 39598525, 2024). "Furthermore, we identified that OCT1 is highly expressed in that AR-negative CRPC-PDX (PDX 201.2), and OCT1 is involved in the AR-independent expression of genes that promote cell migration and tumor proliferation." (PMID 38698344, 2024).
tumor (continued). "These lines of experimental evidence demonstrate the critical role of HGF/MET and Wnt/β-catenin signaling co-activation in promoting tumor progression and inducing AR and SYN double-negative tumor cells, which is similar to what we have observed in PCa patient samples treated with current ADT." (PMID 38336745, 2024). "In summary, since AR expression was generally low in uroepithelial tissues, we concluded that AR was not significantly elevated in either normal or tumour tissues of the bladder, which corroborates DHT plays a role in the pathogenesis of BLCA via a non-AR pathway." (PMID 37328487, 2023). "On immunohistochemical staining, tumor cells were positive for cytokeratin AE1/AE3, p63, and beta-catenin (nuclear and cytoplasmic staining) and negative for HMB45, Melan-A, S-100 protein, and androgen receptor." (PMID 36843770, 2023). "For example, a recent study (PRIMERA trial) including 44 patients revealed that androgen receptor (AR), prostate-specific antigen (PSA), and prostate-specific membrane antigen (PSMA) expression in circulating tumor cells (CTC)+ had no significant impact on PSA drop and survival in mCRPC patients." (PMID 36600256, 2023). "However, the resistance to the PARP inhibitor, the lack of the androgen receptor (45–88% in TNBC), or the rare expression of PD‐L1 in noninflamed tumor cells all dampen the therapeutic efficacy and limit the application of those approaches in TNBC." (PMID 37357618, 2023). "Similarly, the SU2C dataset confirmed our finding that pharmacological inhibition of AR using ARSIs does not inhibit HMMR gene expression, as HMMR remained unchanged by ARSI treatment in CRPC tumours compared to untreated CRPC." (PMID 37673961, 2023). "Indeed, our spatial profiling revealed that the expression levels of AR and its cooperating FOXA141 were not detectable in the hybrid tumor, although their expression levels were found in 20–40% of the parental tumor." (PMID 37848444, 2023). "This could also explain the variation in tumour immunostaining where some tumours are ELF3 negative and some are positive; there could be a correlation with the presence or the absence of AR, as ELF3 is known to act as a repressor of AR." (PMID 35472129, 2022). "Our patient did not benefit from androgen receptor blockade in combination with trastuzumab, thus suggesting that AR expression may simply reflect an intrinsic characteristic of the EMPD cell of origin, rather than tumor dependence upon AR signaling." (PMID 36059635, 2022). "Interestingly, KO of JAK–STAT genes in wild-type sgNT cells or in sgTP53/RB1-KO cells treated with vehicle did not influence tumor cell survival, suggesting a specific role of JAK–STAT signaling in lineage plasticity-driven AR therapy resistance." (PMID 36065066, 2022). "Castration-resistant PDX-derived organoids (PDOs) emerged when they were treated with either of the two main strategies for APDT: depriving the tumor of androgen, that is, no DHT, or direct binding inhibition of the androgen receptor (AR) with the anti-androgen, enzalutamide." (PMID 35328625, 2022). "One explanation for the results showing ELF3 as a repressor is that the experiments were carried out in AR‐responsive LNCaP cells and it is very likely that the advanced cancers where there is amplification of ELF3 would be castration‐resistant tumours where androgen is no longer the driver." (PMID 35472129, 2022). "Although no specific tumour-related gene was shared among the three groups, NOTCH2 was shared between BTG and PTCb while AR, HSP90AB1 and GNAS were shared between BTG and PTCa suggesting their possible roles in the BTG-to-PTCb and BTG-to-PTCa transformation, respectively." (PMID 36686473, 2022).
tumor (continued). "We specifically employed AR-null, enzalutamide-insensitive PC3 cells in these experiments to place emphasis on the effects of enzalutamide on the endothelium as opposed to tumor cells." (PMID 35302608, 2022). "However, after a certain point, the tumor will eventually develop a resistant stage, where ADT and AR antagonists are no longer effective." (PMID 34681745, 2021). "Tissue morphology, presence of luminal markers PSA, NKX3.1, AR, CK8 expression, and absence of CK5+ basal cells indicated stable luminal epithelial morphology among the primary TUR-P tumor (T1), the PNmet, and PDX1–6 passages." (PMID 33602919, 2021). "In contrast, when evaluating the AR negative LAPC9 CRPC model which has primary resistance to enzalutamide, in vivo anti-tumor activity was seen with single agent venetoclax, but there was no additional benefit with the addition of enzalutamide in organoid studies." (PMID 35008216, 2021). "GLS expression is increased post-castration in LNCaP and LAPC4 xenografts, and pharmacological inhibition of GLS1 reduces the tumor burden in PC3, but not LNCaP xenografts, highlighting the dependency on glutamine metabolism in AR-negative, hormone-insensitive prostate cancer." (PMID 35127483, 2021). "Circulating tumor cell (CTC) enumeration and changes following treatment have been demonstrated to be superior to PSA response in determining mCRPC outcome in patients receiving AR signaling inhibitors but not taxanes." (PMID 34066080, 2021). "Tumor grade was significantly negatively correlated with the expression of KRT5 (rs = −0.225; p = 0.029) and showed a trend for a negative correlation with AR (rs = −0.201; p = 0.053)." (PMID 34209360, 2021). "In ER-positive BCa, AR signaling often antagonizes the growth stimulatory effect of ER signaling; in luminal AR subtype of TNBC identified by molecular assays, AR seems to drive tumor progression; in HER2-positive BCa, in the absence of ER expression, AR signaling has a proliferative role." (PMID 32928183, 2020). "The present study used next generation RNA sequencing to identify novel differentially expressed genes in OSA tumor tissue as compared to matched non-tumor tissue and assessed NCOA3 and AR polyQ tract variations in affected and non-affected IWH and Rottweiler dogs." (PMID 32854182, 2020). "Tumor expression of pRPA (P = 0.686) and γ-H2AX (P = 0.798) were not statistically different between the AR+ vs. AR− TNBC cases." (PMID 32964114, 2020). "In addition, the tumor cells were negative for PSA (inset), but positive for androgen receptor, v-ets erythroblastosis virus E26 oncogene homolog (ERG), and alpha-methylacyl-CoA racemase (AMACR)." (PMID 33263827, 2020). "However, till date, only one study has examined AR signaling in GBM, although a limited number of tumor tissues specimens were used, and no statistical analysis was performed." (PMID 28423563, 2017). "The evaluation and interpretation of immunohistochemical AR and FOXA1 expression were not standardized and the use of TMA tumor blocks with small sized cores may not have been able to represent the results of whole sections." (PMID 29137314, 2017). "However, the role of AR in KIRC progression is not clear, as other studies have found negative correlation between AR expression and tumor stage." (PMID 27993167, 2016). "Despite PSA being a well-demonstrated AR target, AR+ cells might not always translate into PSA+ tumor cells." (PMID 26593949, 2015). "Thus, the drop was not a consequence of tumor growth inhibition, but rather an indication of PPD suppression of AR reactivation in the tumors." (PMID 25375370, 2014). "Farmer tumor types by themselves were also prognostic for DSF and OS (log rank p = 0.024 for each), however a survival difference was seen only between HR- and HR + tumors, and was irrespective of an additional AR expression (data not shown)." (PMID 25070172, 2014).